TP63 (tumor protein p63)
Diseases named in the same sentence as TP63 in open-access papers (continued):
Sharing a sentence is not in itself a finding about the gene and the disease.
tumor (continued). "Moreover, consistent observation of the pre-existence of a few TP63-positive cells in parental tumors as well as single-clone derived tumors demonstrates the PC9 tumor plasticity in xenograft assays." (PMID 39687207, 2024). "The decrease in TP63 protein was dependent on growth conditions, since 2D cultures showed unaltered protein levels, which became undetectable when we grew sgTomato or sgSOX2 cells in 3D, that better resemble tumor conditions." (PMID 38951654, 2024). "-FZD7 deletion increased platinum sensitivity, decreased spheroid formation, and delayed tumor formation.- FZD7 expression activated the oncogene Tp63 and metabolic pathways to protect against chemotherapy.- FZD7 expression correlates with residual OCe after chemotherapy." (PMID 39588300, 2024). "To test if decitabine, in turn, could re-establish the promoter hypomethylation of tumor-suppressor genes, we investigated the 5ʹ upstream region of TP63, which may be essential for the integrity of the prostate basal epithelium." (PMID 39766901, 2024). "This study reveals a central regulator of anti-tumor immunity in SCC tumors, provides a potential strategy to turn “immune-cold” SCC tumors into “hot” ones, and suggests TP63 as a candidate biomarker of immune-cold tumor for predicting immunotherapy outcome in SCC patients." (PMID 38509096, 2024). "Nevertheless, most of prior work on TP63 has been focused on its tumor-intrinsic functions." (PMID 38509096, 2024). "In contrast to TN and RD, the tumor biopsy at PD displayed an increase of TP63 expression." (PMID 39687207, 2024). "Consequently, the expression of particular TP63 isoforms has been connected with clinical outcomes across multiple cancer subtypes, and there is a potential tumor suppressive role for TP63 that is more prominent for certain isoforms." (PMID 38793063, 2024). "By integrating bulk transcriptome data, we developed a clinical scoring model based on TP63 and SLC7A5, which are closely associated with tumor stage, revealing the significant prognostic efficacy of the TP63+ SLC7A5+ HNSCC-mediated ferroptosis mechanism in HNSCC patients." (PMID 39234254, 2024). "Additionally, silencing of BCL11A reduced the levels of SCC markers (KRT5 and TP63) and inhibited tumor growth." (PMID 37372998, 2023). "However, EFEMP1 and TP63 were expressed at low levels in tumor tissues and at high levels in normal tissues." (PMID 37441420, 2023). "Recently, a study suggested that TP63 is the maintenance of stem cell pluripotency and plays a unique inhibitory role in tumour progression by regulating cell cycle regulation, extracellular matrix remodel, epithelial-mesenchymal transition, and enrichment of pluripotent stem cells." (PMID 37469408, 2023). "Therefore, the cancer cells mainly expressed the known CSCC‐associated gene SERPINB3 (serpin family B member 3), tumor genes TP63, CDKN2A, and keratin gene KRT5 in squamous cells." (PMID 35986392, 2022). "Moreover, we confirmed that NKX2-1 and TP63 were coexpressed in the same tumor cells by RNA in situ hybridization." (PMID 35962452, 2022). "Because tumor samples may be highly heterogeneous due to tumor type, location, and/or intermixed tissues, we sought to identify potential regulators of TP63 splicing using data from normal tissues." (PMID 36970727, 2022). "TP63 is a tumor protein and acts as a transcription activator suppressor." (PMID 34827731, 2021). "For example, specimen P7 is a LUSC tumor with strong TP63/CK expressions and weak NAPSA expression." (PMID 33953163, 2021).
tumor (continued). "The function of miR-masking oligonucleotides was first described in breast cancer, where the inhibition of the tumor suppressor TP63 could be prevented by miR-196a2 masking oligonucleotide, reducing tumor cell proliferation." (PMID 33672261, 2021). "Reduction in TP63 (ΔNp63) expression by STXBP4 might ameliorate tumor resistance to the current drug treatments and prolong survival of LSCC patient." (PMID 32993587, 2020). "We could identify that TP63 showed the strongest correlation with the SCC cell identity for all tumour subtypes analysed." (PMID 32128997, 2020). "Furthermore, some rare TP63 mutations reported in HNSCC samples are located in the TA domain, suggesting that ΔNp63 isoform expression is positively selected during tumour evolution." (PMID 30845357, 2019). "Notably, the TP63 level was significantly higher in invasive tumor fronts (ITFs) and tumor buddings compared with the superficial or center counterparts." (PMID 28423539, 2017). "Here, we report that TP63 and ΔNp63 regulate tumor growth, metastasis and stemness via miR-138-5p." (PMID 28423539, 2017). "In this study, increased TP63 expression was detected in the ITFs and tumor budding, which indicated that TP63 might play a pivotal role in tumor invasion and metastasis." (PMID 28423539, 2017). "Genes up-regulated in cells from tumor specimens grown under CRC culture conditions are enriched with markers for lung basal cells such as TP63 (> 60 fold), podoplanin (PDPN, > 36 fold), cytokeratin genes KRT6A (> 729 fold), KRT6B (> 98 fold), and adhesion molecules LGALS7B (> 200 fold)." (PMID 28052041, 2017). "With few exceptions, mutations of the TP63 gene are rare in human malignancies, suggesting that it is not a canonical tumor suppressor." (PMID 26203771, 2015). "TP63 is expressed mainly in two isoforms, the TA and N-terminal-truncated (ΔN) forms, and its biological role appears to be more complex than that of a classic tumor suppressor." (PMID 24466311, 2014). "This combination of isoform diversity, widespread genomic occupancy, and post-translational regulation underscores the challenges of identifying the regulatory mechanisms and transcriptional targets of TP63 that account for its complex role in tissue and tumor stasis." (PMID 23166821, 2012). "In addition, depletion of CD8+ T cell with CD8 mAb also resulted in continued tumor growth and elevated tumor weight, strongly suggesting that inhibiting TP63 synergistically enhances the anti-tumor effect of PD-1 mAb by enhancing CD8+ T cell infiltration and activity." (PMID 38509096, 2024). "Notably, we identified a novel tumor immune escape mechanism whereby HNSCC cells may inhibit ferroptosis via TP63, thus sustaining tumor growth and differentiation." (PMID 39234254, 2024). "However, the role of TP63 as a tumour promoter or tumour suppressor has been controversial." (PMID 37469408, 2023).
tumor (continued). "Similarly, it reduced the expression of the TP63; a known suppressor of cell migration and metastasis and could lead to enhanced tumor invasion and migration." (PMID 35805995, 2022). "It was also obvious that CAFs derived from the AT (αSMA-low, SOX2-high, p16+) or BA (αSMA- and EGFR-high and low SOX2/TP63 ratio) mRNA subtypes could support the growth of both types of tumour cells (primary-tumour ones as well as metastatic-derived ones), while CL and ME CAFs were more specific." (PMID 35565415, 2022). "Furthermore, multiple isoforms of TP63 played opposite roles in different human tumours." (PMID 35620407, 2022). "Besides, TP63 expression in tumor cells was related to Ann Arbor stage (P = 0.031)." (PMID 28403071, 2017). "FLRT3 is most strongly co-expressed with tumor suppressor gene TP63 and angiogenesis regulator gene NTN4 (Pearson correlation r = 0.83) (CBioportal), which suggests possible mechanisms by which HNF1B could exert the effects observed here – a control switch preventing EMT in non-tumor tissue." (PMID 27732966, 2016). "We also observed the enrichment of CDKN2A (p16), SERPINB3, KRT5, and TP63, which are well‐established biomarkers for HPV‐positive neoplasia and are typically expressed in tumour areas." (PMID 41362277, 2026). "We propose that HPV oncoproteins E6 and E7 cooperate with these master TFs (TP63, AP-1, and TFAP2A) to nucleate tumor-specific super-enhancer clusters in HPV+ HNSCC." (PMID 41323280, 2025). "The TP63 and TP73 gene structures are complex, involving multiple promoters and splicing variations, which can produce both tumor suppressive and dominant-negative isoforms." (PMID 40227619, 2025). "The analyses identify 3,447 tumor‐specific oncogenic enhancers (SOEs) enriched for master transcription factors (SOX2, TP63, KLF5, GRHL2) that orchestrate malignant programs." (PMID 40899632, 2025). "Subsequently, we treated tumor cells with RSL3 and found that TP63 knockdown increased the sensitivity of the cells to ferroptosis, while TP63 overexpression reduced their sensitivity to ferroptosis." (PMID 40796737, 2025). "In contrast, the ED analysis revealed 204 TFs, with 30 showing substantial tumor-specific TFBS enrichment, including TP63, FOSL1, JUND, JUNB, and KLF5, underscoring their potential roles in tumorigenesis." (PMID 41323280, 2025). "In the case of SED, 225 TFs were analyzed, with TFBSs of 10 TFs identified as enriched in tumor-specific domains (T-SED), including TP63, SMAD3, JUND, and FOSL1/2." (PMID 41323280, 2025). "Previous work demonstrated the tumor-suppressor function of the CDH1 gene, and TP63 has been proposed as genomic target of the oncogene miR-301b, which promotes cell invasiveness in PC through the downregulation of CDH1." (PMID 39791744, 2025). "Several tumor-specific TFs were detected within the ED and SED, including TP63, FOSL1, JUND, GRHL2, SNAI2, KLF5, TP73, and SMAD3." (PMID 41323280, 2025). "Overall, we discovered a unique self-protection mechanism evolved by malignant cells: TP63 regulates SLC7A5 to inhibit ferroptosis, sustain tumor growth and development, and resist immunotherapy." (PMID 39234254, 2024). "Our research elucidates the TME in HNSCC before and after immunotherapy, revealing a novel mechanism by which TP63+ SLC7A5+ HNSCC inhibits ferroptosis and enhances tumor resistance via TP63-induced SLC7A5 upregulation." (PMID 39234254, 2024).
tumor (continued). "TP63 inhibition leads to increased CD8+ T cell infiltration and heighten tumor killing in in vivo syngeneic mouse model and ex vivo co-culture system, respectively." (PMID 38509096, 2024). "A recent study showed that the master transcription factor TP63 in squamous cell carcinomas (SCCs) suppresses IFN-γ signaling, resulting in increased infiltration of CD8+ T cells and enhanced tumor killing." (PMID 38785789, 2024). "TP63 and MYC were sufficient to assign tumours to ACC subtypes, which was validated in one independent cohort by IHC and two additional independent cohorts by RNA-sequencing." (PMID 37795454, 2023). "To address this question, we first used the MGH7 LUSC cell line, which was established in our laboratory and expresses high levels of TP63 and SOX2, and recapitulates the squamous histology of the patient tumor when injected into immunocompromised mice." (PMID 36305267, 2023). "Consistent with our observation that SREBP2 regulates expression of TP63 targets in human SCC cells, we also observed a reduction in ΔNp63 positive nuclei in KPLS2 tumours." (PMID 37202505, 2023). "Expression of proliferation marker Ki76, transcription factor TP63, cytokeratin CK20, and cell surface marker CD24 clearly differed in these different tumor cells upon expansion in BME when compared to cells in GD." (PMID 37626918, 2023). "TP63 is amplified and overexpressed in most OSCC tumors and promotes tumor growth by multiple mechanisms." (PMID 36672394, 2023). "These parameters demonstrated that TP63 was significantly related to patient’s age, lymph node metastasis, TNM stage, and tumor size." (PMID 35480110, 2022). "For P5, the tumor areas on the section were strongly and diffusely positive for NKX2-1 and TP63, and 51% (35,654 out of 70,292 cells analyzed) of the individual cancer cells co-expressed these two markers simultaneously." (PMID 35962452, 2022). "The top downregulated genes [WIF1, DACT2, ID4, TP63, SOX10] in tumours in our transcriptomic profile were regulators of Wnt signalling, cell differentiation and morphogenesis and acted as inhibitors of tumour growth in BC31–34." (PMID 34997107, 2022). "On the other hand, the most supportive were CAFs derived from the ME mRNA subtype of HNSCC tumour mass, characterised by high expression of EMT markers αSMA, vimentin, and desmin and low gene expression of the TP63." (PMID 35565415, 2022). "Similar to TP63, TP73 showed systematically increased expression in the tumor tissues of the SC types." (PMID 35227282, 2022). "In our study, we found that four ADC patients (P5, P10, P11, and P13) had a large proportion of tumor cells coexpressing NKX2-1 and TP63." (PMID 35962452, 2022). "Compared to controls, tumor displaying lower SNAI1, PECAM1 and VIM and higher TP63, KRT14, KRT5 and PTPRC (CD45) RNAs (PyMT-VE-CadhSnail1KO tumor signature) presented a longer overall survival, strengthen our mice results." (PMID 34335957, 2021).
tumor (continued). "Three tumor samples (T5, T16, and T19) exhibited high-level amplification in 3q26, including WWTR1, TP63, PIK3CA, SOX2, SOX2-OT, and ZNF639 genes." (PMID 34285259, 2021). "∆Np63 is essential for the survival of skin and pancreatic SCC cells, since established murine skin SCCs are exquisitely dependent on ∆Np63; acute deletion of TP63 in advanced, invasive SCC induced rapid and dramatic apoptosis and tumour regression." (PMID 32128997, 2020). "It is interesting to note that we also observed a correlation between TP63 and SOX2 expression in single cell RNA-seq analysis of tumor ductal cells from PDA patent samples." (PMID 32329713, 2020). "As expected, many DMGs that were hypermethylated and downregulated in CMT including TP63, LIFR, PLA2G16, LRIG1, STAT5A, and AKAP12 and have been known as tumor suppressors, were identified from high scoring (OncoScore > 50) CMT-DMRs." (PMID 32693820, 2020). "Through the comparative analysis between tumor and matched adjacent normal tissue, we identified large-scale amplification of SOX2 (26/37) and TP63 (24/37) and deletion of CDH1 (25/37) in tumor tissues." (PMID 31695781, 2019). "Under 3D culture, tumor sphere cells formed acinar-like colonies containing both epithelial (EPCAM positive cells) and myoepithelial cells (TP63 positive cells)." (PMID 31196164, 2019). "For example, one finding shows that TP63, TP73, and SOX2 expression in tumor tissues of early, middle, and late stages is higher than that in the adjacent non-tumorous tissues." (PMID 29340250, 2018). "Within this network, several genes were identified namely CCND1, RELA, TP63, and EGFR as being major contributors to tumour cell proliferation, immortalization, and metastasis in oral tumourigenesis." (PMID 28384287, 2017). "Tumor tissues from 76 Chinese DLBCL patients were immunostained for programmed cell death 1 (PD-1), PD-L1, and TP63 using the EnVision system." (PMID 28403071, 2017). "Most of targets for miR-21 have been identified as tumor suppressors, such as PDCD4 (Programmed cell death 4), PTEN, RECK, TP63 and FASLG." (PMID 29190966, 2017). "The two identified homologues, TP63 and TP73, have also been related to apoptosis, and a possible role as tumor suppressors has been suggested." (PMID 25033876, 2014). "Through a comprehensive workflow combining H3K27ac-ChIP-seq and RNA-seq analyses, we identified critical TFs and tumor-specific super-enhancer domains (T-SEDs) that regulate gene expression in HPV+ HNSCC, such as TP63, SMAD3, FOSL2, JUND, JUNB, KLF5, and TFAP2A." (PMID 41323280, 2025). "In this case, the tumour demonstrated ALK1 positivity with the absence of DUSP 22 or TP63 rearrangements, supporting the diagnosis of systemic ALK-positive ALCL." (PMID 41445989, 2025). "Notably, TFs such as TP63, FOSL1, and JUND were enriched in tumor-specific enhancer and super-enhancer domains, indicating their crucial role in tumorigenesis." (PMID 41323280, 2025).